IL6 (interleukin 6)
Diseases named in the same sentence as IL6 in open-access papers (continued):
Sharing a sentence is not in itself a finding about the gene and the disease.
psychosis (continued). "Gene expression analyses conducted only in those cytokines that were different in the serum (IL-1α, IL-1β, IL-6, IL-8 and TNF-α) revealed significantly increased mRNA levels of IL-1α (d = 0.6), IL-6 (d = 0.7) and TNF-α (d = 1.6) in first-episode psychosis patients when compared with controls." (PMID 22749891, 2013). "The results of the ROC analysis in our study showed that IL-2, IL-1β, and IL-10 had significant discriminatory ability in distinguishing the patients with FEDN psychosis from the healthy controls, while IL-6 did not demonstrate a statistically significant value." (PMID 41008291, 2025). "In a further specific classification of NPSLE in the latest research, serum IL-6 and CSF IL-6 were found to be significantly elevated in acute confusion states (ACS) compared to non-ACS diffuse NPSLE (anxiety disorders, cognitive dysfunction, mood disorders and psychosis) or focal NPSLE." (PMID 36133921, 2022). "IL-6 has been suggested as a state-related marker because it has increased during the acute phase and recent relapse-with previous antipsychotic use- and in patients with the first episode of psychosis without medication and has been normalized with long-term antipsychotic treatment." (PMID 37644489, 2023). "In addition, approximately 30 patients with psychosis without evidence of inflammation (IL-6<0.7 pg/mL) and 30 matched healthy controls will be recruited to complete identical baseline assessments to allow for comparison of the characteristic features of inflammation-associated psychosis." (PMID 36963796, 2023). "A large part of the variance in negative symptoms, psychosis, hostility, excitation, mannerism, psychomotor retardation and formal thought disorders was explained by the combined effects of EM2 and MOR with or without IL-6 while increased KOR was significantly associated with all symptom dimensions." (PMID 32858974, 2020). "Youth with TPD had higher IL-6 (Hedge’s g = 0.35, 95%CI0.11 – 0.64,k = 4,N = 258,I2 = 0%) compared to youth without psychosis in the meta-analysis." (PMID 38141839, 2024). "Our meta-analysis found that neutrophil/lymphocyte ratio, TNF, CRP, IL-6, and total WBC were elevated in youth with threshold psychosis compared to youth without threshold psychosis, extending results from adult populations." (PMID 38141839, 2024). "Although IL-6 and TNF-α have been already previously suggested as a possible important target for patients with treatment-resistant psychosis and with prevalent negative syndrome, the findings of increased IL-10 were more unexpected." (PMID 33667853, 2021). "This was recently confirmed in first episode psychosis patients, where non-responders to treatment had significantly lower CAR and significantly higher IL-6 and IFN-γ levels than responders to treatment." (PMID 28358316, 2017). "As hypothesized, meta-analyses found elevations of biomarkers often considered “proinflammatory,” specifically neutrophil/lymphocyte ratio, TNF, CRP, IL-6, and total WBC, in youth with threshold psychosis compared to youth without psychosis." (PMID 38141839, 2024). "An updated review in 2019 reported increasing levels of IL-6, TNF-α, and IL-1β in different groups of patients, including first-time psychosis without medication and patients with first-time psychosis who were often treated with antipsychotics and chronic patients and patients with acute recurrence." (PMID 37644489, 2023).
Myocardial fibrosis (119 papers, 2012 to 2026). "The molecules TGF-β1, TNF-α, IL-6, galectin-3, and galectin-1 are critically involved in the cardiac inflammatory and profibrotic cascade, and they have been linked to myocardial fibrosis severity and to structural and electrical atrial remodeling." (PMID 41590667, 2026). "Myocardial fibrosis is intricately linked to chronic inflammation, in which IL-6 serves as a pivotal pro-inflammatory cytokine contributing to the pathogenesis of myocardial fibrosis." (PMID 41150746, 2025). "Interleukin‐6 (IL‐6), a proinflammatory cytokine, has been implicated in myocardial fibrosis and hypertrophy across multiple cardiovascular diseases." (PMID 41377766, 2025). "This study's observational design precludes establishing causality between elevated IL‐6 levels, genetic mutations, and myocardial fibrosis." (PMID 41377766, 2025). "Increase in CVD risk factors increases IL‐6 production from cardiac fibroblast cells and induces myocardial fibrosis via the transforming growth factor‐β1 signalling pathway." (PMID 39264256, 2024). "IL-6 played a crucial role in aldosterone-induced macrophage recruitment and infiltration of myocardial macrophages, causing myocardial fibrosis." (PMID 38566090, 2024). "It releases proinflammatory cytokines such as tumor necrosis factor-alpha, interleukin-1-beta, and interleukin-6, which can cause variable irreversible changes in the myocardium structure, including myocardial fibrosis." (PMID 31347351, 2019). "Recent studies point toward regulatory effects of IL-6 in pathological fibrosis where IL-6 infusion in rats caused LV hypertrophy and myocardial fibrosis." (PMID 25997003, 2015). "Experimental evidence supports this mechanism: in models of left ventricular pressure overload and diabetic cardiomyopathy, genetic deletion of IL-6 significantly alleviates myocardial fibrosis and associated dysfunction, whereas IL-6 overexpression exacerbates the fibrotic phenotype." (PMID 41150746, 2025). "Moreover, IL-6 inhibition in hypertensive specimens has been linked to decreased myocardial fibrosis and inflammation." (PMID 31186952, 2019). "Another study showed that interleukin-6 was elevated in the blood of patients with PA, and related studies have suggested that interleukin-6 may be secreted by vascular endothelial cells and causes myocardial fibrosis." (PMID 35625856, 2022). "In summary, the inflammatory factor IL-6 promotes the development of myocardial fibrosis by activating inflammatory signaling pathways such as MAPK and STAT3 and activating TGFβ-1 growth factor." (PMID 40881586, 2025). "Prior research indicates that CFs can promote their own transdifferentiation via IL-6 production and also exert paracrine effects on cardiomyocytes and other cardiac cell types, thereby exacerbating myocardial fibrosis." (PMID 41150746, 2025). "Non‐ApHCM patients with elevated IL‐6 levels exhibited the highest myocardial fibrosis burden and the worst clinical outcomes, likely reflecting a complex interplay between genetic predisposition and chronic inflammation." (PMID 41377766, 2025). "Carfilzomib exacerbates these effects by activating the NF-κB pathway in cardiac tissue, promoting inflammatory cytokine release (e.g., TNF-α, IL-6) and myocardial fibrosis." (PMID 40969263, 2025). "High levels of IL-6 during cardiopulmonarybypass likely contribute to myocardial fibrosis through JAK/STAT activation." (PMID 40026508, 2025). "The JAK2/STAT3 pathway is activated by the binding of inflammatory cytokines, such as IL-6, to its specific receptor and stimulates the expression of cytokines, such as IL-6, thereby increasing the inflammatory response and promoting myocardial fibrosis." (PMID 40881586, 2025). "In terms of mechanism, it has been suggested that it works together with proinflammatory cytokines such as Interleukin-6 in a positive feed-back loop to enhance inflammation and promote myocardial fibrosis." (PMID 40564042, 2025).
Myocardial fibrosis (continued). "TLR4 is involved in regulating myocardial fibrosis and hypertrophy by modulating pro-inflammatory factors such as interleukin-6 (IL-6)." (PMID 41300325, 2025). "QL inhibits IL-6 mediated transformation of myocardial fibroblasts, thereby suppressing myocardial fibrosis and cardiac remodeling." (PMID 40881586, 2025). "Persistent NF-κB activation promotes chronic low-grade inflammation, characterized by overexpression of TNF-α, IL-1β, and IL-6, which contributes to cardiomyocyte apoptosis and myocardial fibrosis." (PMID 41158877, 2025). "Future research endeavors will incorporate animal models to further validate the roles of MG-EWE and its monomeric compounds, Laurolitsine and Hecogenin, in anti-myocardial fibrosis and IL-6 production inhibition." (PMID 41150746, 2025). "And sterile inflammation is closely associated with the levels of pro-inflammatory factors (e.g., TNF-α, IL-6, and IL-1β) that can induce myocardial fibrosis." (PMID 40881586, 2025). "Cytokines such as interleukin-1, interleukin-6, tumor necrosis factor-alpha, and interleukin-17 are involved in promoting myocardial fibrosis, ion channel dysfunction, and autonomic dysregulation, which contribute to arrhythmic events." (PMID 40901119, 2025). "These processes, combined with upregulated pro-inflammatory cytokines (e.g., TNF-α, IL-6), foster myocardial fibrosis and electrical remodeling." (PMID 41011065, 2025). "As IL-6 has been shown to promote LV hypertrophy and myocardial fibrosis, it is of specific interest that tissue expression of IL-6 mRNA and protein was increased at both time-points in diabetic mice and was suppressed by hUC-MSC injection." (PMID 38659015, 2024). "Conversely, the production of IL-6 by cardiac fibroblasts induces myocardial fibrosis through activation of the TGFß pathway." (PMID 39285385, 2024). "Proinflammatory cytokines such as TNF-α and IL-6 stimulate cardiac oxidative stress and coronary artery dysfunction, leading to cardiac remodeling, myocardial fibrosis, and diastolic dysfunction." (PMID 39365793, 2024). "TMAO and betaine were also significantly associated with myocardial fibrosis measures, and elevated TMAO correlated with cardiac and MT markers like sCD14, NT‐proBNP, troponin‐I, galectin‐3, GDF‐15, and IL‐6." (PMID 39652612, 2024). "In stress overload-induced myocardial fibrosis, elabela and Fer-1 alleviate late concomitant myocardial fibrosis via the IL-6/STAT3/GPX4 signaling pathway." (PMID 39358326, 2024). "It amplifies Ang II-induced cardiac inflammation, promoting the production of pro-inflammatory factors such as IL-6 and macrophages, thus influencing macrophage polarization and intensifying macrophage-mediated myocardial fibrosis." (PMID 38622341, 2024). "Studies in mice with autoimmune myocarditis revealed that silencingmiR-21a-5p resulted in a significant reduction in TNFα, IL-6 andcollagen I expression, reducing excessive infiltration of damaging myocardialcells and inhibiting myocardial fibrosis formation." (PMID 39077397, 2023). "IL-6 was a downstream signal molecule of cadherin-11 and had a central role in myocardial fibrosis, and cardiomyocyte hypertrophy, which was mediated by activating the MAPKs and CaMKII-STAT3 pathways." (PMID 37047522, 2023). "Cardiac involvement may be caused by myocarditis, myocardial fibrosis, vasculitis, or microvascular dysfunction, which is associated with chronic inflammatory responses resulting from autoimmune diseases, such as the effects from inflammatory agents like IL-6 and INF-α." (PMID 36483559, 2022). "CASR not only significantly improved the degree of myocardial fibrosis, inflammatory infiltration, and blood viscosity but also reduced the levels of IL-6, ET, TC, and LDL-C and increased the level of HDL-C." (PMID 36016561, 2022).
Myocardial fibrosis (continued). "Proinflammatory cytokines such as tumor necrosis factor (TNF-α), interleukin 1β (IL-1β), and interleukin 6 (IL-6) can inhibit myocardial contraction, promote myocardial fibrosis, and increase collagen synthesis in pathological cardiac hypertrophy." (PMID 36270989, 2022). "IL6 also acts as an inflammatory factor whose expression promotes cardiac fibroblasts, thereby increases collagen synthesis and eventually leading to myocardial fibrosis." (PMID 34692849, 2021). "In our study, we demonstrated relationships between tEAT and levels of pro-inflammatory cytokines (TNF-α and IL-6), adipokines (leptin and adiponectin), and markers of myocardial fibrosis (MMP-3, TGF-β, and collagen)." (PMID 34088886, 2021). "At week 15, Il6 expression (which is a well-known mediator of myocardial fibrosis leading to concentric hypertrophy and secondary DD) remained high." (PMID 34884782, 2021). "Using mIF methods, we have demonstrated presence of IL-1B and IL6 activity within collagen fibers in the regions of myocardial fibrosis, both of which have been known to play a profibrotic role." (PMID 34765640, 2021). "Although IL-6 has been described as a myocardial fibrosis promoter, it also has significant capacity to modulate murine neonatal cardiomyocyte proliferation by enhancing relevant protein expression and subsequently promoting cardiac regeneration." (PMID 33420256, 2021). "IL-6 infusion in rats for 7 days in vivo resulted in a smaller and stiffer LV with increases in cardiomyocyte width and length and LV mass, all of which were most likely due to IL-6-induced myocardial fibrosis." (PMID 32932869, 2020). "The expression of inflammatory factors such as tumor necrosis factor-α (TNF-α) and interleukin-6 (IL-6) was demonstrated to promote cardiac fibroblast proliferation, thereby increasing collagen synthesis and ultimately leading to myocardial fibrosis." (PMID 31885827, 2019). "AF patients indicated a higher concentration of TNF-α and IL-6, lymphomonocyte infiltration, as well as the degree of myocardial fibrosis." (PMID 30386232, 2018). "Cyclophosphamide (CTX) induces myocardial fibrosis and cardiac hypertrophy, as well as changes in the expressions of several cytokines, such as interleukin (IL)-2, IL-10, IL-6, and TNF-α, which can further facilitate the occurrence and development of AF." (PMID 30386232, 2018). "In summary, deletion of IL-6 is able to mitigate myocardial fibrosis and improve cardiac function of diabetic mice." (PMID 26972749, 2016). "It decreased myocardial fibrosis and transmurality of the infarct, associated with increased eNOS, p-eNOS, and IL-10 along with decreased expression of TNF-α, IL-6 and iNOS." (PMID 25807532, 2015). "For example, IL-6 is involved in the development of myocardial fibrosis in other experimental settings." (PMID 24775918, 2014). "It has been shown that IL-6 directly mediated myocardial fibrosis by inducing a conversion in fibroblast phenotype to myofibroblasts." (PMID 22574112, 2012). "We critically examine how loss-of-function mutations in epigenetic regulators promote a pro-inflammatory macrophage phenotype through NLRP3 inflammasome activation and IL-1β/IL-6 signaling, thereby accelerating atherogenesis, plaque instability, and myocardial fibrosis." (PMID 42039360, 2026). "Interestingly, the peptide hormone Elabela inhibited myocardial fibrosis inmouse models by suppressing the IL-6/STAT3 signalling pathway and activatingthe cystine–glutamate antiporter xCT/glutathione peroxidase pathway." (PMID 40026508, 2025). "The anti-inflammatory properties of the Mediterranean diet, driven by its high content of omega-3 fatty acids, polyphenols, and monounsaturated fats, reduce the pro-inflammatory cytokine profile of EAT, including TNF-α and IL-6, which are known to promote myocardial fibrosis and dysfunction." (PMID 39860003, 2025).
Myocardial fibrosis (continued). "Furthermore, IL-6 can promote myocardial fibrosis by activating the TGF-β1 pathway or interfering with myocardial metabolism, worsening the overall condition of HF patients through multiple mechanisms." (PMID 41479659, 2025). "This study aims to elucidate the active components and underlying molecular mechanisms by which the ethanol-water extract of Cinnamomum migao H.W. Li (MG-EWE) inhibits cardiac fibroblast transdifferentiation and IL-6 production, providing insights into its anti-myocardial fibrosis effects." (PMID 41150746, 2025). "Therefore, inhibiting IL-6 production by CFs is a promising therapeutic strategy to prevent CF transdifferentiation and slow the progression of myocardial fibrosis." (PMID 41150746, 2025). "The reduction in pro-inflammatory monocytes led, on one hand, to a decrease in pro-inflammatory cytokines such as IL-1 and IL-6, which in turn reduced myocardial fibrosis, which would ultimately contribute to reduced myocardial fibrosis and improved cardiac function." (PMID 41299461, 2025). "Furthermore, QJ decreased collagen deposition and IL-6 levels in vivo, implying that QJ had a potential effect on anti-inflammation and a decreased degree of myocardial fibrosis." (PMID 35140803, 2022). "PTX3 can counteract the myocardial fibrosis by inhibiting the IL-6/STAT3 pathway, implicating that PTX3 KD may acts as a therapeutic target for HF after MI." (PMID 35522573, 2022). "IL-6 has been shown to have a critical role in aldosterone-induced macrophage recruitment and infiltration of myocardial macrophages, which play an important role in myocardial fibrosis." (PMID 35548430, 2022). "In addition, the differentiation of Th17 cells often requires transforming growth factor-β and interleukin (IL)-6, which are involved in myocardial fibrosis development." (PMID 34593936, 2021). "IL-6 has shown profibrotic effects, determining both vascular and myocardial fibrosis." (PMID 31186952, 2019). "In addition, TNF induces cardiomyocyte apoptosis, and IL6 induces hypertrophy and myocardial fibrosis." (PMID 28163696, 2017). "IL-6 directly mediated myocardial fibrosis, hypertrophy, and diastolic dysfunction." (PMID 22574112, 2012). "In addition, IL-6 can regulate the development of high glucose-induced myocardial fibrosis by enhancing the expression of TGF-β1 and inhibiting the expression of miR-29, which promotes the regulation of myocardial fibroblast proliferation and collagen production." (PMID 40881586, 2025). "During this process, inflammatory mediators such as C-reactive protein and interleukin-6 are continuously activated, leading to myocardial cell damage, restricted myocardial energy metabolism, and inhibition of functional recovery through the induction of myocardial fibrosis." (PMID 41393266, 2025). "Interleukin-6, interleukin-1 beta and the tumour necrosis factor (TNF)-alpha may cause myocyte damage via the major histocompatibility complex-1, by local nitric oxide release and myocardial fibrosis." (PMID 36088383, 2022). "Th17 cells may promote myocardial fibrosis through serial effectors, such as IL-6 and TNF-α." (PMID 23977238, 2013). "In summary, CDDP regulates inflammatory response mainly by affecting factors such as TNF-α, NF-κB, IL-6, JNK, KDM4A, and FOXO1, thus inhibiting myocardial fibrosis and improving cardiac function." (PMID 40881586, 2025). "Monocyte activation, IL-6, TNF-α production, and NLRP3 inflammasome activation are heightened in CRS, contributing to vascular and myocardial fibrosis." (PMID 40806569, 2025). "IL-6 and TNF-α can accelerate the secretion of a large amount of collagen and myocardial fibrosis in myocardial tissue, and finally damage myocardial function." (PMID 40547034, 2025). "It reduced the expression of IL-6, IL-1β, and matrix MMP9, inhibited cell division and proliferation to inhibit myocardial fibrosis." (PMID 38469405, 2024).